LIMK1 (LIM domain kinase 1)
Diseases named in the same sentence as LIMK1 in open-access papers (continued):
Sharing a sentence is not in itself a finding about the gene and the disease.
prostate carcinoma (32 papers, 2007 to 2024). A carcinoma that arises from epithelial cells of the prostate gland. "Previous studies have confirmed that ectopic expression of LIMK1 was associated with the progression of several tumor types, such as colorectal cancer, gastric cancer, prostate cancer, and breast cancer." (PMID 34149814, 2021). "In prostate cancer, it is reported that elevated LIMK1 is positively associated with higher Gleason Scores and incidence of metastasis, as well as poor clinical outcome and reduced survival." (PMID 34149814, 2021). "Nonetheless, our study strongly suggests an association between expression of LIMK1 and prostate cancer." (PMID 17559677, 2007). "In this study, the consequence of overexpression of LIMK1 in prostate epithelial cells, and any association of LIMK1 with prostate cancer have been assessed." (PMID 17559677, 2007). "For example, an immunohistochemical (IHC) study in prostate cancer found an association between the amount of nuclear LIMK1, higher Gleason scores, and incidence of metastasis, suggesting that nuclear LIMK1 may contribute to progression of human cancer." (PMID 21682918, 2011). "LIMK1, which is found to be upregulated in prostate cancer samples and cancer cell lines, also seems to play a role in prostate cancer pathogenesis." (PMID 36899941, 2023). "LIMK1 and LIMK2 are overexpressed in prostate cancer and prostate cell lines, and numerous LIMK partners that are dysregulated in prostate cancer have been discovered over the last years." (PMID 36899941, 2023). "It has also been reported that motility and invasion capacity of breast and prostate cancer cells (with overexpressed LIMK1) was attenuated when inhibitors of upstream LIMK regulators are administered." (PMID 34843456, 2021). "Many studies support an oncogenic role for LIMK1 in colorectal cancer, lung cancer, prostate cancer and osteosarcoma." (PMID 30873211, 2019). "Another previous study reported that GRP78 led to the activation of PAK-2 and LIMK1 to accelerate the metastasis in prostate cancer." (PMID 29849883, 2018). "LIMK1 enhances nuclear androgen receptor translocation, leading to prostate cancer cell proliferation and survival." (PMID 29970879, 2018). "PAK4 regulates cell migration mainly dependent on the downstream pathways of LIMK1/cofilin in prostate cancer and gastric cancer." (PMID 28440035, 2017). "Our results showed that GL-1196 effectively suppressed the invasive capability of gastric cancer cells in conjunction with downregulation of PAK4/LIMK1/cofilin pathway, much as previously revealed in prostate cancer cells." (PMID 27077843, 2016). "Together, these data suggested that LIMK1-cofilin signaling played an important role in the regulation of prostate cancer cell migration by miR-23a." (PMID 25714010, 2015). "LIMK1 overexpression increases the invasiveness of breast and prostate cancer cells in vitro and in vivo, and knocking down of LIMK1 suppresses breast and prostate cancer cell invasion in vitro and in vivo." (PMID 24858712, 2014). "Increased Limk1 expression has been found in prostate tumor tissues, and is involved in regulating the invasiveness of prostate cancer cells." (PMID 25003638, 2014). "High levels of LIMK1 have been observed in highly invasive prostate cancer cell lines and in human prostate tumors." (PMID 21219645, 2011). "This is consistent with previous studies reporting that ectopic expression of LIMK1 in breast and prostate cancer cell lines increased cellular invasion." (PMID 21682918, 2011). "We chose BPH-1 cells, which was originally isolated from benign prostatic hyperplasia, for ectopic expression of LIMK1 as these cells express low levels of LIMK1 compared to the metastatic prostate cancer cells PC3." (PMID 21219645, 2011). "Further studies are required to assess the relevance of LIMK1- mediated deregulation of cell cycle in progression of prostate cancer." (PMID 17559677, 2007).
prostate carcinoma (continued). "PAK6 can also directly regulate prostate cancer cell metastasis through LIMK1." (PMID 36230657, 2022). "PAK4 promotes prostate cancer cell migration via its kinase substrates such as LIMK1." (PMID 36230657, 2022). "This study aimed to explore the association between LIM domain kinase 1 (LIMK1) expression in prostate cancer (PCa) tissues with advanced pathological features, lymph node metastases and biochemical recurrence." (PMID 32168432, 2020). "Additional analyses revealed that miR-23a directly targeted the p21-activated kinase 6 (PAK6) gene to suppress the phosphorylation of LIM kinase 1 (LIMK1), resulting in cytoskeletal reorganization, and ultimately, the inhibition of prostate cancer cell invasion and metastasis." (PMID 25714010, 2015). "Therefore, next we studied the effect of expression of LIMK1 on MT1-MMP concentration in prostate cancer cells." (PMID 21219645, 2011). "Indirect evidence based on comparative genomic hybridization analysis have indicated a significant correlation between high-stage prostate cancers and chromosomal gains in the short arm of chromosome 7 (7q11.2), which includes the region where LIMK1 is located (7q11.23)." (PMID 17559677, 2007). "Expression of LIMK1 may deregulate mitotic checkpoints in cancer cells whereby it can promote development of resistance of advanced prostate cancer to taxenes." (PMID 17559677, 2007). "To assess whether there is any correlations between expression of LIMK1 and prostate cancer we have evaluated the staining profile of LIMK1 in a number of prostate tumors from patients with history of metastasis using immunohistochemistry." (PMID 17559677, 2007). "Thus, the interaction between PAK4 and LIMK1 could be an essential factor in prostate cancer invasiveness." (PMID 36899941, 2023). "A previous report showed that LIMK1 could increase MMP2 expression in prostate cancer." (PMID 34079084, 2021). "Moreover it has been proposed that LIMK1 itself could behave as a MAP: it was shown in prostate cancer cells that LIMK1 physically interacts with tubulin." (PMID 28445157, 2017). "Previous studies in prostate cancer have also shown that miR-143-3p can inhibit cell growth through various targets, including KRAS, Bcl-2, ERK5, LIMK1, HK2 and KLK2." (PMID 37759434, 2023). "Our experiments showed that in prostate cancer cells, the expression levels of E-cadherin and beta-catenin didn't change no matter LIMK1 was knockdown or over-expressed (data not shown)." (PMID 25714010, 2015). "The level of expression of LIMK1 achieved in our experiment was either parallel to or less than that noted in advanced prostate tumors and in PC3 prostate cancer cells; this suggests that over expression of LIMK1 in prostate tumors may suffice to elicit the biological effects noted here." (PMID 17559677, 2007). "We have noted that LIMK1 but not LIMK2 is overexpressed in highly aggressive and metastatic PC3 prostate cancer cells and in prostate tumor tissues compared to benign prostatic hyperplasia (BPH-1) cells and normal prostatic epithelium." (PMID 17559677, 2007).
colorectal cancer (27 papers, 2014 to 2026). A primary or metastatic malignant neoplasm that affects the colon or rectum. "In colorectal cancer tissue specimens, LIMK1 upregulation was found to be associated with lower overall survival rates as well as increased lymph node metastasis potential." (PMID 37371647, 2023). "Furthermore, an association between LIMK1 and miR-27b was shown for colorectal cancer and A-549 cells." (PMID 33829040, 2021). "LIM domain kinase 1 (LIMK1), a novel β-catenin kinase highly expressed in colorectal cancer and associated with poor prognosis, promotes malignant progression through its interaction with STK25, which enhances cell proliferation and metastasis." (PMID 41614944, 2026). "Suppression of YTHDC2 in colorectal cancer cells impairs binding to m6A modification sites on LiM kinase 1 (LIMK1) mRNA, thereby enhancing its stability and upregulating expression." (PMID 40986143, 2025). "LIMK1 has been demonstrated to be highly correlated with the progression and overall survival rates of colorectal cancer (CRC) patients." (PMID 41246964, 2025). "A previous study has shown that LIMK1-mediated phosphorylation of cofilin promoted colorectal cancer progression, and silence of LIMK1/cofilin pathway abrogated tumor cell growth and metastasis." (PMID 35350839, 2022). "LIMK1 was reported to be overexpressed in colorectal cancer tissues and functioned as a competitive inhibitor of LIMK2 to promote the nuclear translocation of β-catenin, thus promoting tumor progression through activation of the Wnt/β-catenin pathway." (PMID 35350839, 2022). "Notably, B7-H3 expression showed a positive correlation with LIM domain kinase 1 (LIMK1) expression in colorectal cancer (CRC) tissue, revealing that B7-H3-depleted cells exhibited a reduced expression of RhoA, ROCK1, and LIMK1." (PMID 40214484, 2025). "Aberrant overexpression of LIMK1 drives eIF2α hyperphosphorylation, triggering endoplasmic reticulum stress and enhancing stress granule assembly, which collectively culminates in resistance to 5-FU in colorectal cancer cells." (PMID 40986143, 2025). "Additionally, studies have shown that IRX5 can negatively regulate RhoA/ROCK1/LIMK1 signaling pathway to promote the metastasis of colorectal cancer cells." (PMID 34486491, 2021). "YTHDC2 was downregulated in colorectal cancer (CRC), leading to increased stability and expression of LIM domain kinase 1 (LIMK1) mRNA in CRC cells." (PMID 38790013, 2024). "Results showed that ROCK1, LIMK1, MMP3, and MMP9 mRNA expressions were down-regulated after ALKAL1 silencing in colorectal cancer RKO and SW480 cells." (PMID 33391411, 2021). "The imbalanced expression of LIMK1 and LIMK2 could promote β-catenin nuclear translocation and activate the wnt signaling pathway, thus leading to colorectal cancer progression." (PMID 36901953, 2023). "In addition, LIM domain kinase 1 (LIMK1), which is overexpressed in colorectal cancer, promotes cell motility and proliferation via Akt signaling, and ACTN4 is a downstream target gene of LIMK1 in colorectal cancer." (PMID 33363146, 2020).
lung cancer (23 papers, 2015 to 2025). A malignant neoplasm involving the lung. "Previous studies have implicated the parent gene LIMK1 in poor prognosis and increased immune infiltration in lung cancer, suggesting a pivotal role for LIMK1 and its associated circRNAs in LUAD progression." (PMID 40593477, 2025). "Taken together, these results provide insight into the mechanism that underlies the anticancer effects of luteolin on lung cancer, which involved in down‐regulation of LIMK1 and its interaction with cofilin." (PMID 33982869, 2021). "LIMK1 is overexpressed in lung cancer and is associated with high tumor-nodes-metastasis (TNM) stage and lymph node metastasis." (PMID 25975262, 2015). "Given the overexpression of LIMK1 in lung cancer and the downregulation of LIMK1 can inhibit lung cancer cell migration, we hypothesized that the level of LIMK1 is associated with survival in lung adenocarcinoma." (PMID 34149814, 2021). "LIMK1 is a serine/threonine kinase associated with the cytoskeletal structure in many cellular processes, and may have importance in the sensitivity of lung cancer and osteosarcoma cells to chemotherapy treatment." (PMID 27822437, 2016). "Western blot analysis of human gastric cancer and lung cancer specimens confirmed that LIMK1/CDK5 protein expression was significantly increased in primary tumors and further enhanced in matched metastatic tumor tissues compared to adjacent normal tissues." (PMID 40476449, 2025). "It has also been demonstrated that luteolin inhibits the in vitro and in vivo proliferation of lung cancer cells by targeting LIMK1." (PMID 35678671, 2022). "This study aims to investigate the anticancer effects of luteolin on human lung cancer cells by targeting LIMK1." (PMID 33982869, 2021). "Many studies about the oncogenic role of LIMK1 in several human cancers have been emerged in recent years, including gastric cancer, pancreatic cancer, as well as lung cancer." (PMID 34149814, 2021). "In this study, we found that luteolin has the potential to treat lung cancer due to its ability to regulate a new target LIMK1/cofilin signalling pathway." (PMID 33982869, 2021). "Hsa_circ_0012673 combines with miR-320a and thereby regulates LIMK1 expression and promotes the progression of lung cancer." (PMID 34992655, 2021). "Current study provides a message useful for moving dasatinib toward the treatment for patients with lung cancer and shows the prospective translational potential of dasatinib for patients with lung cancer who were accompanied with high expression of LIMK1." (PMID 33344441, 2020). "In summary, our results indicate that dasatinib acts as a novel LIMK1 inhibitor to suppress the lung cancer cell proliferation in vitro and tumor growth in vivo, which suggests evidence for the application of dasatinib in lung cancer therapy." (PMID 33344441, 2020). "Altogether, we unveil that the inhibitory activities of dasatinib against lung cancer cells are realized by regulating LIMK1 activity directly and LIMK1/cofilin signaling pathway." (PMID 33344441, 2020). "Herein, we demonstrated that dasatinib dose-dependently blocked lung cancer cell proliferation and repressed LIMK1 activities by directly targeting LIMK1." (PMID 33344441, 2020). "To verify the role of LIMK1 in lung cancer cells, we first infected shMock or shLIMK #1, #2, and #3 to NCI-H1650 cells, and results of western blot exhibited that LIMK1 expression was lowered by shLIMK in comparison with shMock." (PMID 33344441, 2020). "Knockdown of LIMK1 inhibits migration of lung cancer cells and enhances sensitivity to chemotherapy drugs." (PMID 30873211, 2019). "Our finding is consistent with previous report that knockdown of LIMK1 can suppress the migration and invasion of lung cancer cells." (PMID 28440035, 2017). "LIMK1, a downstream effector of PAK4, has been reported to be up‐regulated in lung cancer and associated with high tumor metastasis and lymph node metastasis." (PMID 28440035, 2017).
lung cancer (continued). "Moreover, gastric cancer and lung cancer patients with high LIMK1 expression had markedly shorter survival times according to the TCGA database." (PMID 40476449, 2025). "Furthermore, luteolin has been shown to inhibit lung cancer cell proliferation by blocking LIMK1 and its related signaling pathways, leading to cell cycle arrest and apoptosis." (PMID 37990309, 2023). "Moreover, some recent findings suggested that downregulation of LIMK1 can inhibit lung cancer cell migration." (PMID 34149814, 2021). "Previous trials suggest that LIMK1 may be a target of dasatinib which can inhibit LIMK1 to suppress lung cancer cell proliferation and growth." (PMID 34149814, 2021). "Thus, LIMK1 has great potential to be a biomarker of poor prognosis and therapeutic target for lung cancer." (PMID 34149814, 2021). "In addition, miR-320a was shown to be associated with EMT regulation by the suppression of the LIM domain kinase 1 (LIMK1), a serine-threonine protein kinase in lung cancer cells." (PMID 33833996, 2021). "It was confirmed that knockdown of LIMK1 expression suppressed lung cancer cell proliferation." (PMID 33344441, 2020). "For in vitro experiments, dasatinib inhibited LIMK activity by negatively regulating the phosphorylation of the LIMK1 substrate, cofilin, which resulted in growth inhibition, apoptosis and cell cycle arrest in lung cancer cell lines that were highly expressed LIMK1." (PMID 33344441, 2020). "The down-regulation of LIMK1 could inhibit the growth of lung cancer and GBM." (PMID 36341390, 2022). "Furthermore, si-LIMK1 suppressed the migration and invasion of lung cancer cells." (PMID 25975262, 2015). "In this study, combination therapy with LIMK1 and CDK5 inhibitors exhibited a significant therapeutic effect on ESCC metastasis in a preclinical setting, as well as in EAC, gastric cancer, and lung cancer metastasis." (PMID 40476449, 2025). "High expression of LIMK1 and CDK5 is associated with poor prognosis of ESCC patients, and the clinical and functional significance of LIMK1/CDK5‐Wnt/β‐catenin axis is also verified in esophageal adenocarcinoma, gastric cancer, and lung cancer." (PMID 40476449, 2025). "The Boyden chamber assay showed that LIMK1/CDK5 significantly promoted the invasion of EAC, gastric cancer, and lung cancer cells in a phosphorylation‐dependent manner." (PMID 40476449, 2025). "The clinical and functional significance of the LIMK1/CDK5‐Wnt/β‐catenin axis was also verified in esophageal adenocarcinoma, gastric cancer, and lung cancer." (PMID 40476449, 2025). "LIMK1 has been shown to participate in the EMT process by affecting the actin cytoskeleton, and was found to be up-regulated in lung cancer cells." (PMID 33833996, 2021). "Silencing Rac1 significantly inhibited the EMT phenotype in lung cancer cells, accompanied with a significant down-regulation of RAC1, PAK1, p-PAK1, LIMK1, p-LIMK1, Cofilin, and p-Cofilin in lung cancer cells." (PMID 32411607, 2020). "In the present study, we found that IR promoted lung cancer cell EMT in the process, accompanied with an up-regulation of RAC1, PAK1, p-PAK1, LIMK1, p-LIMK1, Cofilin, p-Cofilin in these cells." (PMID 32411607, 2020). "Hsa_circ_0012673 promotes cell proliferation in lung cancer tissues and cells through regulation of LIM domain kinase 1 (LIMK1) levels by sponging miR-320a." (PMID 32587475, 2020). "However, how modulating LIMK1 promotes lung cancer cell migration remains unclear." (PMID 25975262, 2015). "Furthermore, LIMK1/CDK5 also increased the phosphorylation of β‐catenin in both gastric cancer and lung cancer cells." (PMID 40476449, 2025). "Additionally, we explored the clinical and functional significance of the LIMK1/CDK5‐Wnt/β‐catenin axis in esophageal adenocarcinoma, gastric cancer, and lung cancer." (PMID 40476449, 2025).